RNU6-1199P (RNA, U6 small nuclear 1199, pseudogene)
Gene: Small nuclear RNA gene on chromosome 1 (758,233 to 758,336, reverse strand). Ensembl gene ENSG00000223181.
Homologues: Orthologues: macaque U6 (90% identical), pig U6 (83% identical), pig U6 (77% identical), dog U6 (76% identical). Paralogues in human: RNU6-1076P (99% identical), RNU6-1100P (99% identical), RNU6-1118P (99% identical), RNU6-1217P (99% identical), RNU6-355P (99% identical), RNU6-447P (99% identical), RNU6-785P (99% identical), RNU6-791P (99% identical), RNU6-860P (99% identical), U6 (99% identical), RNU6-1054P (98% identical), RNU6-1319P (98% identical), and 1289 more.